PTH (parathyroid hormone)
Diseases named in the same sentence as PTH in open-access papers (continued):
Sharing a sentence is not in itself a finding about the gene and the disease.
hypovitaminosis D (continued). "Low 25-hydroxyvitamin D levels are found and suggest hypovitaminosis D. PTH is increased along with high alkaline phosphatase." (PMID 39301310, 2024). "Both cases were clinically inconsistent with rickets based on normal calcium, phosphorous, and parathyroid hormone concentrations; however, Case 1 had hypovitaminosis D (9 nmol/L) compared to healthy juvenile black bears." (PMID 39061550, 2024). "Although expected, according to the study protocol, the hypovitaminosis D evident in the Orthodox nuns group resulted in significantly higher median serum PTH than among the lay women (45.6 vs. 19.4, p < 0.001) after adjusting for seasonal variation." (PMID 39408266, 2024). "Every 1–3 months, patients with rickets should have blood work done to evaluate their calcium, phosphate, alkaline phosphatase, and PTH values." (PMID 39301310, 2024). "Reliance solely on skeletal benefits (e.g., preventing rickets in children and osteomalacia in adults and maintaining physiological circulatory PTH levels) for recommending vitamin D intake and 25(OH)D blood levels is flawed and must be abandoned." (PMID 39599755, 2024). "Laboratory findings and radiographic evidence further support a diagnosis of rickets, with increased alkaline phosphatase activity, decreased calcium, and normal parathyroid hormone (PTH) values." (PMID 37858137, 2023). "The first line biochemical assessment in the rickets diagnostic workup includes serum ALP, in addition to serum calcium, phosphorus, 25OH-vitamin D (25OHD) and parathyroid hormone (PTH) evaluation." (PMID 36817604, 2023). "A low cut-off was chosen because children with increased PTH levels and those suffering from osteomalacia or rickets had 25- OHD3 levels." (PMID 38126603, 2023). "Elevation of PTH differentiates between calcipenic and phosphopenic rickets and should be measured in initial screening blood tests for rickets." (PMID 37074534, 2023). "Multiple cross-sectional studies have shown a negative correlation between 25-(OH)D levels and PTH and report contradictory results for cut-off points and a prevalence of increased PTH of 10–33% in patients with hypovitaminosis D." (PMID 37359435, 2022). "During hypovitaminosis D or hypocalcemic phases, PTH concentrations increase and the osteoclast becomes its main target cell in bone; in this way, it activates bone resorption." (PMID 35750999, 2022). "Biochemical measures include serum phosphate, calcium, and alkaline phosphatase (ALP) as a surrogate marker of osteoblast activity and thus degree of rickets, parathyroid hormone (PTH), and 25-hydroxyvitamin D3 (25(OH)D)." (PMID 35352187, 2022). "As expected, considering the marked hypovitaminosis D, about half of the patients presented PTH values higher than 65 pg/mL." (PMID 35742610, 2022). "The significant reduction in the PTH levels obtained as a result of the correction of hypovitaminosis D marks a meaningful improvement in the patient’s cardiovascular risk profile." (PMID 35807864, 2022). "All but one had elevated alkaline phosphatase (ALP) levels, a marker for active rickets, whereas some also had elevated PTH and FGF23 levels." (PMID 33869987, 2021). "Serum 25(OH)D, PTH, ALP, Ca, and Pi level dosage are helpful to confirm the diagnosis and also to differentiate nutritional rickets to other causes of rickets." (PMID 34199067, 2021). "Optimal control of rickets, PTH and ALP should be achieved before growth hormone therapy is considered in children with XLH." (PMID 33815294, 2021). "The measurement of plasma calcium (preferably ionized if feasible, or alternatively albumin-corrected), phosphate, ALP, creatinine, PTH and 25(OH)D are part of the standard work-up for any form of rickets or osteomalacia." (PMID 33815294, 2021). "A concurrent serum PTH measurement can be useful when distinguishing between calciopenic (PTH should be elevated) and phosphopenic rickets (PTH likely within normal laboratory reference range or only modest elevation)." (PMID 33614549, 2021).
hypovitaminosis D (continued). "Studies on the threshold of ALP and PTH under subclinical hypovitaminosis D are limited and variable." (PMID 33330264, 2020). "In this study, there was also a tendency to higher serum ALP and PTH levels in neonates with hypovitaminosis D than the values in normal-25(OH)D group." (PMID 33330264, 2020). "Further, PTH levels are commonly about the upper normal range at diagnosis of XLH while being typically elevated in nutritional rickets." (PMID 31993875, 2020). "When he was diagnosed with VDDR1A, he had elevated PTH levels and typical radiological findings of rickets." (PMID 30282619, 2019). "In BPD/DS patients having hypovitaminosis D despite full oral supplementation, a single injection of 600,000 IU of cholecalciferol was effective in normalizing intact PTH and vitamin D levels." (PMID 29869004, 2018). "Further evaluation of hypocalcemia revealed raised ALP and PTH, and low 25OHD of 12.5 nmol/L and rickets on knee radiograph." (PMID 29940979, 2018). "A single injection of 600,000 IU of cholecalciferol was effective in restoring and maintaining normal levels of vitamin D and PTH for 6 months in BPD/DS patients with hypovitaminosis D, despite full oral supplementation." (PMID 29869004, 2018). "Most population screening studies to date have used clinical signs, biochemical markers (raised ALP and PTH, low calcium, low 25OHD) and radiological signs to define rickets, either in isolation or in combination." (PMID 28612338, 2017). "Further, elevated PTH and pubescent skeletal growth and development modulate the manifestation of rickets in FHH patients." (PMID 28690912, 2017). "We present the clinical phenotype of a toddler who presented with vitamin D-resistant rickets, with one of the highest initial levels of alkaline phosphatase and parathyroid hormone (PTH) levels reported in the literature." (PMID 28620554, 2017). "The classical RD contains 2% calcium and 1.25% phosphorus, and is considered to be able to normalize serum levels of calcium and parathyroid hormone (PTH) and to prevent rickets in these mice." (PMID 28443031, 2017). "Plasma PTH levels in the children with hypovitaminosis D were significantly higher than in the children with normal levels of vitamin D (4.34 ± 1.38 vs 3.78 ± 1.25 pmol/L; P-value = 0.04)." (PMID 25886311, 2015). "They reported a single oral dose of 300,000 IU followed by oral vitamin D3 of 800–1000 IU is effective in correcting hypovitaminosis D and PTH level." (PMID 23803739, 2013). "Our findings highlight the complex interactions between PTH and hypovitaminosis D, which merit further study." (PMID 24073266, 2013). "This raises the intriguing possibility that reduced PTH response in the presence of hypovitaminosis D is a protective mechanism, which should be explored further." (PMID 24073266, 2013). "The rise in PTH was delayed and less distinct, perhaps because of only a modest degree of hypovitaminosis D. Furthermore, the rise of 1,25(OH)2D, as induced by the calcium insufficiency, is known to suppress PTH secretion." (PMID 24062955, 2013). "Even though there was no increase in 25OHD values among women, the proportion of those who had hypovitaminosis D decreased significantly, which can explain the significant PTH reduction observed in this group in the summer." (PMID 20546572, 2010). "The role of parathyroid hormone in this process is still the subject of controversy but the sequence of events from hypovitaminosis D to rickets/osteomalacia as already understood in the 1960’s remains valid today." (PMID 22254068, 2010). "We do not know how long these children have been suffering from hypovitaminosis D. For this reason, ALP and PTH concentrations of subjects with hypovitaminosis D should be followed at long term." (PMID 21318069, 2008). "This includes i) high PTH activity resulting in calcipenic rickets, ii) inadequate phosphate absorption from the gut or iii) renal phosphate wasting which both result in phosphopenic rickets." (PMID 40295317, 2025).
hypovitaminosis D (continued). "The strategy of long-term low-dose supplementation also enables effective treatment of hypovitaminosis D. The doses used (500 or 1000 IU) increased serum 25(OH)D concentrations and were sufficient to decrease PTH concentrations (p < 0.001), thereby preventing bone decalcification." (PMID 39861482, 2025). "The proposed mechanisms include direct viral interaction with ACE2 receptors in the parathyroid gland, viral chelation of calcium, worsening hypovitaminosis D, critical illness leading to unbound fatty acids binding calcium, and inflammatory cytokines leading to PTH resistance." (PMID 39355148, 2024). "The higher prevalence of hypovitaminosis D in CS and PS could be also related to the inhibition of PTH." (PMID 38807014, 2024). "In patients with untreated calcemic rickets, markedly elevated PTH levels may be observed in order to maintain normal serum calcium levels." (PMID 37047636, 2023). "In some children, calcimimetic Cinacalcet may be required to prevent the rise in PTH while allowing oral phosphorus to heal rickets." (PMID 37074534, 2023). "It has also been proposed that hypovitaminosis D could promote a physiological elevation of parathyroid hormone (PTH) levels by increasing the intracellular calcium concentration in adipocytes which, in turn, would stimulate lipogenesis and weight gain." (PMID 36771474, 2023). "With regard to obesity hypovitaminosis D in affected subjects could at least be partially explained by VitD storage in adipose tissue, and low VitD leads to both elevated PTH and increased calcium in adipocytes with influence on lipogenesis and adiposity." (PMID 37892428, 2023). "Management includes close monitoring of growth, the degree of leg bowing, bone pain, serum phosphate, calcium, alkaline phosphatase as a surrogate marker of osteoblast activity and thus degree of rickets, parathyroid hormone, 25-hydroxyvitamin D3, and calciuria." (PMID 35352187, 2022). "Normalization of serum ALP, calcium, phosphate, and PTH levels indicates healing of rickets." (PMID 35352187, 2022). "In contrast, patients with calcipenic rickets/osteomalacia arising from nutritional vitamin D and/or dietary calcium deficiency or VDDR (types IA, IB, IIA and IIB, and III) have markedly elevated plasma PTH levels." (PMID 33660084, 2021). "The elevated PTH in the presence of normocalcemia might reflect a subclinical or mildly clinical hypovitaminosis D." (PMID 34113519, 2021). "In most patients, we found hypovitaminosis D and high levels of parathyroid hormone (PTH)." (PMID 34876084, 2021). "Parameters of calcium metabolism, including serum levels of calcium, Pi, PTH and vitamin D (both 25-hydroxy and 1,25-dihydroxy) are usually within normal range, and may help in the differential diagnosis from rickets." (PMID 34884378, 2021). "The major consequence of hypovitaminosis D is bone remodeling, which correlates to PTH levels." (PMID 32821633, 2020). "An inverse relationship between vitamin D and parathyroid hormone (PTH) indicates that hypovitaminosis D may have an indirect effect on CVD." (PMID 33425213, 2020). "Apart from rickets and osteomalacia, high PTH concentrations, which may occur secondary to vitamin D deficiency, are associated with increased cortical bone porosity and associated increased risk of fracture." (PMID 33659951, 2020). "The low phosphate interferes with chondrocyte maturation at the growth plate (rickets) and, together with relatively low calcium, reduces mineralization of osteoid (osteomalacia) while the increased PTH increases bone resorption, resulting in cortical bone porosity and increased fracture risk." (PMID 33659951, 2020). "A high prevalence of hypovitaminosis D combined with high PTH levels and lower bone mineral density has recently been reported in Finnish girls and Italian children and adolescents, suggesting that Italian children are at risk for this condition, as well as other European populations." (PMID 30053889, 2018).
hypovitaminosis D (continued). "In BPD/DS patients, having hypovitaminosis D despite full oral supplementation, a single injection of 600,000 IU of cholecalciferol was effective in elevating vitamin D levels and normalizing levels of intact PTH." (PMID 29869004, 2018). "For these reasons, some authors proposed HVDRR to be a form of PTH-dependent rickets." (PMID 27796266, 2017). "This inverse relationship between serum 25(OH)D and serum PTH indicates hypovitaminosis D in the study subjects, although there is less information on specific cut-off value for serum vitamin D [25(OH)D] deficiency and insufficiency which can demark the level between sufficiency and insufficiency." (PMID 28473985, 2017). "Diagnosis is based on clinical findings (long bone deformities, enlargement of wrists and costochondral junctions), typical biochemical abnormalities (increased ALP and PTH) and radiological changes of rickets (cupping, splaying and fraying of metaphyses, widened growth plates and low bone mass)." (PMID 28612338, 2017). "It is well established that hypovitaminosis D might result in increased PTH values and may mask a more significant evaluations in serum Ca, because of reduced Ca absorbtion." (PMID 27901181, 2016). "PTH levels above the upper quartile (44 pg/mL) occurred in 32% of hypovitaminosis D patients." (PMID 26955207, 2016). "Vitamin D is also inversely associated with parathyroid hormone, although this change is not seen in all patients with hypovitaminosis D, and excess parathyroid hormone has been related to increased risk of heart failure." (PMID 25970442, 2015). "Approximately 40% of our patients with hypovitaminosis D showed a reduced response to PTH." (PMID 24073266, 2013). "Thus, to investigate the role of PTH in the regulation of IGFBP-4 levels, we prospectively measured serum IGF-I, IGFBP-3, IGFBP-4 and PTH concentrations in infants with nutritional rickets before and after treatment." (PMID 21274331, 2010). "In kidneys, the parathyroid hormone stimulates osteoclasts to increase bone resorption and maintain blood calcium levels, while the impaired renal phosphate absorption and the decreased phosphate levels may lead to nutritional rickets and osteomalacia." (PMID 38540656, 2024). "It is hypothesized that hypovitaminosis D in obesity would stimulate PTH secretion, which in turn would increase the renal hydroxylation of vitamin D. This would promote calcium influx into adipocytes, thus promoting lipogenesis and suppressing lipolysis and exacerbating fat deposition." (PMID 36291463, 2022). "Depending on the severity of rickets, vitamin D and calcium supplementation may already result in normalization of serum calcium and phosphate levels and a significant decrease in PTH levels within 3 weeks, whereas normalization of ALP levels may take several months." (PMID 35352187, 2022). "The clinical presentations of patients with VDDR1A could lead to a misdiagnosis of nutritional rickets or hypophosphatemic rickets, which can be differentiated from hypophosphatemic rickets by a high PTH level and from nutritional rickets by a normal 25-OHD level." (PMID 30282619, 2019). "However, possible new causes for this impairment in KS patients may be related to specific mechanisms of KS, such as an important hypovitaminosis D and higher PTH levels, aspects that are also present before the puberty onset." (PMID 27413371, 2016). "Therefore, this animal model could be used to study the effects of exclusive hypovitaminosis D in many different experimental settings to mimic human disorders with only minimal potentially confounding effects of PTH and minerals." (PMID 25815325, 2015). "Serum calcium, phosphate, alkaline phosphatase, parathyroid hormone (PTH), and vitamin D metabolites are crucial biochemical parameters for the diagnosis of the various forms of rickets." (PMID 38706696, 2024).
hypovitaminosis D (continued). "The PTH mean values also increased, although remaining within the normal range, at both the baseline and 12 months post-LSG, probably because of hypovitaminosis D that alters intestinal calcium absorption." (PMID 39771007, 2024). "If serum levels of PTH, ALP, phosphorus and calcium are normal, the diagnosis of rickets is unlikely." (PMID 36817604, 2023). "However, sex, age, socioeconomic level, phototype, solar exposure score, smoking and bone mass index, were not statistically associated with hypovitaminosis D. The study of relationship between vitamin D status and serum PTH levels showed a significative and negative correlation (P < 0.005)." (PMID 35510205, 2022). "In laboratory tests, ionized calcium and 25-hydroxivitamin D3 [25(OH)D3] were below the minimum reference range and, although the serum PTH concentration was within the reference range for the species, authors suspected the presence of SNH, along with rickets." (PMID 33901261, 2021). "For the diagnosis of nutritional rickets, although there are several serum biochemical tests, such as 25(OH)D, calcium, phosphate, alkaline phosphatase (ALP) and PTH, clinical symptoms and radiography, there are still defects in sensitivityand specificity." (PMID 33015068, 2020). "They all had low serum levels of 25 hydroxyvitamin D (25OHD < 15 nmol/L), and elevated parathyroid hormone (PTH; 219–482 ng/L) and alkaline phosphatase (ALP; 802–1123 IU/L), with undiagnosed rickets on radiographs." (PMID 29940979, 2018). "After 4 months of cinacalcet, serum Ca and P levels were within normal limits and we also observed sustained control of serum PTH and ALP levels and healing of the radiological rickets findings." (PMID 27796266, 2017). "This response cannot be explained by the type of definition of hypovitaminosis D used (IOM) because according to its definition only participants with serum levels of 25 (OH) D lower than 12 ng/mL and with normal serum PTH levels were considered." (PMID 29149839, 2017). "In a study comparing serum levels of ALP and PTH in HR, VDDR and nutritional rickets, the highest serum levels of PTH and ALP have been found in patients with VDDR and the lowest levels in patients with HR." (PMID 29280738, 2017). "After adding cinacalcet to the treatment schedule, PTH and ALP levels decreased, serum Ca and P levels were sustained within normal levels, and complete radiological healing of rickets was observed." (PMID 27796266, 2017). "No patients with hypovitaminosis D presented osteomalacia based on clinical and serological characteristics (in particular parathyroid hormone sera levels and alkaline phosphatase levels) and the normal value of bone mineral density at densitometry." (PMID 36982443, 2023). "An increase in PTH secretion is aimed to normalize 1,25(OH)2D3 serum concentrations (hypovitaminosis D diminishes negative feedback regulation on PTH) to maintain intestinal calcium absorption." (PMID 35090436, 2022). "When calcium absorption in the gut does not work efficiently because of the hypovitaminosis D, PTH concentration enhances this process." (PMID 31770397, 2019). "Although VitD interacts with PTH signaling, hypovitaminosis D does not influence PTH under sufficient serum levels of Ca." (PMID 30609750, 2019). "In the current series, despite of the low calcium consumption besides hypovitaminosis D, BS group did not present a higher median serum PTH." (PMID 28724055, 2017). "Our data interestingly seems to suggest that PTH levels were significantly higher in KS patients than in controls, even in absence of severe hypovitaminosis D, suggesting that KS patients tend to increase PTH levels more than the general population." (PMID 27413371, 2016). "In multivariate analysis, the enhancing effect of hypovitaminosis D on PTH secretion was independent of common confounding factors herein associated." (PMID 24618074, 2014).